MCHR1 (melanin concentrating hormone receptor 1)
Diseases named in the same sentence as MCHR1 in open-access papers (continued):
Sharing a sentence is not in itself a finding about the gene and the disease.
colonic adenocarcinoma (1 paper, 2012). "We first examined expression of MCHR1 on human colonic adenocarcinomas and in mouse LGR5 positive intestinal stem cells." (PMID 22848656, 2012). "In humans, we detected expression of MCHR1 in normal colonic epithelial cells as well as in colonic adenocarcinoma cells." (PMID 22848656, 2012).
epilepsy (1 paper, 2025). A brain disorder characterized by episodes of abnormally increased neuronal discharge resulting in transient episodes of sensory or motor neurological dysfunction, or psychic dysfunction. "Analyses with ILAE‐sourced epilepsy yielded that genetically predicted higher levels of MCHR1 were strongly associated with an increased risk of GE." (PMID 40170563, 2025). "MR analysis identified 14 drug target genes causally associated with epilepsy or its subtypes and identified MCHR1 and SIGMAR1 as drug target genes of interest for future studies in epilepsy." (PMID 40170563, 2025). "A meta‐analysis of epilepsy from both sources suggested that higher levels of MCHR1 were significantly associated with an increased risk of GE (OR: 1.09, 95% CI: 1.04 ‐ 1.16, p = 0.001)." (PMID 40170563, 2025). "Higher levels of ADRA1Dand MCHR1 were associated with a higher risk of epilepsy." (PMID 40170563, 2025).
fibrosis (1 paper, 2021). the formation of excess fibrous connective tissue in an organ or tissue in a reparative or reactive process. "Inhibition of MCHR1 should be considered as a novel therapeutic strategy in SSc-associated fibrosis." (PMID 34912333, 2021).
Hepatic steatosis (1 paper, 2021). Steatosis is a term used to denote lipid accumulation within hepatocytes. "The contribution of MCHR1 to fibrotic responses is demonstrated in patients with inflammatory bowel disease, and severe hepatic steatosis in mice." (PMID 34912333, 2021).
Hydrocephalus (1 paper, 2019). Hydrocephalus is an active distension of the ventricular system of the brain resulting from inadequate passage of CSF from its point of production within the cerebral ventricles to its point of absorption into the systemic circulation. "As observed in MCHR1 knockout mice, a lack of MCHR1 provokes an increase in ventricular size and could eventually lead to a hydrocephalus." (PMID 29948643, 2019).
intestinal tumors (1 paper, 2012). "One intriguing and unexpected finding in the present study is the demonstration of MCHR1 expression in LGR5-positive crypt stem cells, which are considered to play a key role in the development of intestinal tumors." (PMID 22848656, 2012).
ischemia (1 paper, 2017). A hypoperfusion of the BLOOD through an organ or tissue caused by a PATHOLOGIC CONSTRICTION or obstruction of its BLOOD VESSELS, or an absence of BLOOD CIRCULATION. "As observed for Pmch its receptor Mchr1 was also increased during the acute phase of ischemia (at 4h and 24h following ischemia) in both groups which, underwent ischemia (IS and SD_IS groups) compared to Sham group." (PMID 28061506, 2017).
osteoporosis (1 paper, 2024). A condition of reduced bone mass, with decreased cortical thickness and a decrease in the number and size of the trabeculae of cancellous bone (but normal chemical composition), resulting in increased fracture incidence. "Lastly, we test that MCHR1 agonist is capable of attenuating osteoporosis in mice." (PMID 39320347, 2024). "To investigate the effect and therapeutic potential of MCHR1 signaling in skeletal senescence, we intravenously delivered both MCHR1 agonist (MCH TFA) and antagonist (ALB‐127158a) or vehicle (saline) for age induced osteoporosis in mice." (PMID 39320347, 2024). "Activating these neurons increases MCH levels, promoting bone marrow stromal cell differentiation and osteogenesis via MCHR1‐PKA signaling, suggesting potential therapeutic targets for osteoporosis and skeletal senescence." (PMID 39320347, 2024).
systemic lupus erythematosus (1 paper, 2024). An autoimmune multi-organ disease typically associated with vasculopathy and autoantibody production. "A. annua, on the other hand, increased systemic lupus erythematosus (ko05322) and melanin-concentrating hormone receptor 1 (ko04320), while dTMP kinase (ko00943) and ko04622 decreased (p < 0.05)." (PMID 39314884, 2024).
cancer (3 papers, 2012 to 2023). A tumor composed of atypical neoplastic, often pleomorphic cells that invade other tissues. "Because we had detected MCHR1 in human carcinomas, we next measured the in vitro effects of MCH on Caco2 cells." (PMID 22848656, 2012).
psychiatric disorder (3 papers, 2017 to 2021). A disorder characterized by behavioral and/or psychological abnormalities, often accompanied by physical symptoms. "Thus, the study of PDLIM5‐based interaction networks focused on MCHR1‐bearing primary cilia will contribute to improving the understanding of mental illnesses and serve as a basis for developing potential therapies targeting the primary cilia." (PMID 34485842, 2021).
vasculopathy (1 paper, 2021). "Increased levels of MCHR1 can also potentially mediate the vasculopathy characteristic of SSc." (PMID 34912333, 2021). "Vasculopathy is one of the most common features of SSc, and MCHR1 has not been previously reported to contribute to angiogenesis or vasculopathy." (PMID 34912333, 2021).
MCHR1 also shares sentences with these, for which no sentence is quoted: tumor (5 papers); anemia (3); Insulin resistance (3); Autoimmunity (2); colorectal cancer (2); endocrine diseases (2); infection (2); iron deficiency (2); metabolic disease (2); Arthritis (1); autoimmune hepatitis (1); cardiovascular diseases (1); cervical cancer (1); chronic fatigue syndrome (1); clear cell renal cell carcinoma (1); CNS demyelinating disease (1); glioma (1); hypersomnia (1); Hypertension (1); narcolepsy (1); Nervous (1); neurological disorders (1); nicotine addiction (1); obesity syndrome (1); psoriasis (1); Salmonella Infections (1); sleep disorder (1); type 2 diabetes (1); Ventriculomegaly (1).